OR5AK2 (olfactory receptor family 5 subfamily AK member 2)
Description:
Odorant receptor.
Tractability: Antibody: UniProt places it where antibodies can reach, with medium confidence; UniProt predicts a signal peptide or a membrane-spanning region; its Gene Ontology location is reachable by antibodies, with medium confidence.
Gene: Protein-coding gene on chromosome 11 (56,988,914 to 56,989,843, forward strand). Ensembl gene ENSG00000181273.
Subcellular location: Cell membrane
Pathways (Reactome):
Sensory Perception: Expression and translocation of olfactory receptors
Gene Ontology:
Molecular function: olfactory receptor activity; G protein-coupled receptor activity
Biological process: G protein-coupled receptor signaling pathway; sensory perception of smell; detection of chemical stimulus involved in sensory perception of smell
Cellular component: plasma membrane; membrane
Genetic constraint (gnomAD): Missense variants: 412 observed, 360.85 expected, observed/expected ratio (o/e) 1.14, 90% interval 1.05 to 1.24. Synonymous variants: 167 observed, 123.11 expected, observed/expected ratio (o/e) 1.36, 90% interval 1.2 to 1.54.
Homologues: Orthologues: chimpanzee OR5AK2 (97% identical), dog OR5AK7 (78% identical), rat Or5ak25 (76% identical), rat Olr440 (75% identical), mouse Or5ak23 (75% identical), rat Or5ak24 (75% identical), mouse Or5ak24 (75% identical), mouse Or5ak25 (74% identical). Paralogues in human: OR5AK3P (83% identical), OR5B12 (52% identical), OR5B3 (50% identical), OR5B21 (50% identical), OR5P3 (50% identical), OR8U3 (50% identical), OR5AP2 (49% identical), OR5F1 (49% identical), OR5J2 (49% identical), OR8U1 (48% identical), OR9H1 (48% identical), OR5D18 (48% identical), and 84 more.